CD44 (CD44 molecule (IN blood group))
Diseases named in the same sentence as CD44 in open-access papers (continued):
Sharing a sentence is not in itself a finding about the gene and the disease.
cancer (continued). "However, there are interesting observations from the studies of cancer cells pertaining to interactions between CD44 and HA vis-à-vis the efflux pump in these cells affecting efficiency of the P-glycoprotein in removing anticancer drugs of known genotoxicity." (PMID 22383371, 2012). "Many studies refer to CD44 as a commonly expressed surface marker in different cancer types." (PMID 22693526, 2012). "Also, in our preliminary study on selected cancer cell lines, we observed a range of variation in CD44 and CD24 expression even amongst same cancer types." (PMID 22693526, 2012). "CD44 can regulate cancer stem cell tumorigenesis by promoting matrix assembly, allowing the local concentration of glycosaminoglycan-associating proteins such as FGF2 and VEGF and promoting migration and the epithelial-mesenchymal transition, which is a critical step in invasion and metastasis." (PMID 22567280, 2012). "Taken together, these results suggest that lowering cholesterol levels may disturb the regulated CD44 membrane localization that is necessary for enhanced cancer cell adhesion and migration." (PMID 22253629, 2012). "In addition, CD44 is known to defend cancer cells against oxidative stress by increasing reduced glutathione synthesis." (PMID 22215106, 2012). "Both CD44- and CD44v-positive stem cell-like phenotypes have been reported to have high-capacity antioxidant systems rich in glutathione that result in growth arrest, cell differentiation, and senescence and thereby promote the proliferation of cancer cells." (PMID 22577245, 2012). "CD133+/CD44+/CXCR4+ cells represent a highly tumorigenic subset of cancer progenitors and targeting CXCR4 signaling may be beneficial in eliminating this subpopulation." (PMID 22359577, 2012). "Besides directly engaging cell-matrix and -cell adhesions, CD44 facilitates cancer progression and serves as a marker for cancer-initiating cells." (PMID 22679508, 2012). "Despite CD44 being highly expressed in comparison to other cancer types, CD44 variant expression does not seem to be fundamentally deranged in OPSCC carcinoma lines." (PMID 22242150, 2012). "CD44 is also known to be essential for the homing and engraftment of the cancer stem cells." (PMID 22768192, 2012). "Both CD44-enriched and CD44-depleted cancer cell populations contained cells that could contribute to mouse/human chimeric mammary outgrowths." (PMID 23155468, 2012). "Additionally, CD44 gene expression levels can be compared among various cancer types, other diseases, and cell lines." (PMID 22242150, 2012). "In addition, miR-199a-3p has multiple targets in different cancer types (especially with cancer cells that are CD44 positive) and appears to play a more dominant role than miR-199a-5p." (PMID 22942713, 2012). "Many studies have investigated CD44 as a biomarker for cancer, including BCa." (PMID 22629457, 2012). "To examine whether CD44+CD24-ESA+ or CD44+CD24+ESA+ cells are cancer stem-like cells and to further investigated their tumorigenic potential, we implanted 10,000, 1,000, and 100 cells into the mammary fat pads of nude mice." (PMID 22901246, 2012). "Similarly expression of some isoforms of CD44 in particular types of cancer can correlate with good prognosis, and suppress metastasis in animal models." (PMID 22916191, 2012). "When compared to CD44- cells, CD44+ cells form tumors in mice much more efficiently, show increased invasion, and exhibit markedly higher resistance to chemotherapy drugs, all hallmarks of cancer stem cells." (PMID 23300583, 2012). "NOS2 was associated with additional cancer biomarkers in these tumors, including pAkt, down stream targets p-caspase-9, and pBAD, as well as the stem cell marker CD44 in ER negative tumors." (PMID 22957045, 2012).
cancer (continued). "In many cancers, CD44 plays a major role in initiation, metastasis, and promoting tumourigenesis; while other studies opposed this relationship in other human cancers like breast and prostate cancers, where its high expression also showed no carcinogenesis." (PMID 22693526, 2012). "CD44 appears to have a significant regulatory role in almost all cancer types and more elucidations on this marker may contribute to evaluate its prognostic importance." (PMID 22693526, 2012). "CD44 and CD147 are associated with cancer metastasis and progression." (PMID 22870202, 2012). "The cell surface proteoglycan CD44 has been recognized as a cancer stem cell marker." (PMID 23213537, 2012). "Stro-1, CD105, CD44 are the cancer stem cell marker for bone cancer." (PMID 22082307, 2011). "CD133, CD44, Integrin 12b1 are the cancer stem cell marker for prostate cancer." (PMID 22082307, 2011). "Hyaluronan and CD44 have been shown to influence drug resistance through several mechanisms including cell survival signaling pathways, drug transporter expression and activity, glycolytic phenotype, and cancer stem-like cell characteristics." (PMID 21637840, 2011). "CD44 and Musashi-1 showed consistent expression pattern in both intestinal type and diffuse type cancer, with respect to their localisation in the adjacent normal area and cancer." (PMID 21829201, 2011). "However, cancer cells which highly expressed CD44 were also reported to be enriched for TICs in several other types of human cancers." (PMID 21731740, 2011). "The down-regulation of CD44 has been reported in other cancer types, including carcinoma arising from the progression to dysplasia in Barrett's esophageal epithelium, metastatic endometrial cancer, high-grade bladder transitional cell carcinoma, prostate cancer, and high-grade brain tumors." (PMID 21819617, 2011). "The expression pattern of CD44 showed contradictory results in various cancer types." (PMID 21819617, 2011). "However, we observed variability in the number, distribution, and location of CD44+ cancer cells amongst patients." (PMID 21904548, 2011). "Because of the ability to bind cell surface CD44, which is upregulated in many cancer types, HA has been conjugated or co-admininistered with traditional chemotherapy drugs to increase the direct targeting of the drug to the cancer cells." (PMID 21541039, 2011). "It is intriguing to speculate that these two populations actually represent meroclones or paraclones and that the CD44-High, Vimentin-High are holoclones that harbor stem-like cancer cells that has been reported for PC3 cells in culture." (PMID 24212937, 2011). "We detected CD44+ cancer cells in all but one tissue section tested." (PMID 21904548, 2011). "HA, which has a high molecular weight, is widely distributed in the extracellular matrix (ECM), and could potentially combine with CD44 and participate in cell migration and cancer progression." (PMID 21749678, 2011). "Although statistically significant, this increase was small in the primary samples (∼15%), but in the CD44 sorted pure cell populations miR-137 went from nearly fully methylated in cancer to unmethylated in normal, with corresponding expression patterns of the mature miRNA." (PMID 22132151, 2011). "Experimentally, soluble CD44 overexpression blocks cancer cell adhesion to HA." (PMID 22216242, 2011). "In addition to being enriched in prospective stem cell signatures, OTBCs were enriched in the tumorigenic, cancer stem cell CD44+/CD24- signature." (PMID 21952072, 2011). "CD44 is a polymorphic family of immunologically related cell surface proteoglycans and glycoproteins, normally takes part in cell-cell and cell-matrix adhesion interactions, which is involved in cancer cell migration, proliferation and metastasis." (PMID 21669008, 2011). "Interestingly, AK1C1, AK1C3, AL1A1, and CD44 have been reported to be biomarkers of cancer stem cells (see Discussion)." (PMID 21888658, 2011).
cancer (continued). "CD44 is also one of the most common markers for isolating cancer stem-like cells, which are a highly malignant subpopulation of cells that display drug and radiation resistance and have been characterized in many cancers." (PMID 21637840, 2011). "Notably, CD90+CD44+ subpopulations had stronger capacity of tumorigenesis and metastasis than CD90+CD44- subpopulations, and the proportion of CD90+CD44+ subpopulations in metastasis increased compared to primary cancer." (PMID 21542915, 2011). "CD44, BMI-1 are the cancer stem cell marker for head and neck cancer." (PMID 22082307, 2011). "Interestingly, DZNeP treatment also increased the CD44-/24+ fraction, which is represented by more differentiated cancer cells." (PMID 21501485, 2011). "Similarly, some recent studies also indicate that both HA and CD44 are involved in chemotherapeutic drug resistance in many cancers." (PMID 21749678, 2011). "Therefore they are novel splicing events and elongate the list of the ten CD44 cancer-specific variable exons." (PMID 20700505, 2010). "In addition, disseminated cancer cells in bone marrow with CD44+/CD24- phenotype have been identified in patients, although the prognostic relevance of this is as yet unclear." (PMID 20691079, 2010). "Furthermore, the knockdown of snail expression significantly decreased the expression of ALDH1, inhibited cancer stem-like properties, and blocked the tumorigenic abilities of CD44+CD24−ALDH1+cells." (PMID 21461395, 2010). "The expression of CD44 has been reported to be induced by lactosis in cancer cells." (PMID 20844768, 2010). "Future studies focusing on these genes may help to identify drugs that target the CD44+/CD24- subpopulation of cancer cells, as has been demonstrated recently using human mammary epithelial cells depleted of E-cadherin or overexpressing TWIST." (PMID 20691079, 2010). "CD44 plays a crucial role in inflammation and in cancer progression." (PMID 21151997, 2010). "As an important adhesion molecule, CD44 plays a major role in cancer cell migration." (PMID 21311095, 2010). "Interestingly, CD44+ subpopulation of cells with cancer stem cell properties has been identified in HNSCC and various other cancer types." (PMID 19602232, 2009). "CD133, CD44, Nanog, and Oct-4 are known to be the common markers of cancer stem cell for HNSCC." (PMID 19917110, 2009). "In addition, the LNCaP CD44+CD24− cells are an attractive model system to understand the biology of cancer stem cells and their transition into later progenitor cells." (PMID 18268494, 2008). "The present work demonstrates that tumorigenic CD44+CD24−/low (CD24−) cells can originate from primary CD44lowCD24+ (CD24+) human mammary epithelial cells (HMECs) following their transformation with a limited number of oncogenes and cancer-associated genes." (PMID 18682804, 2008). "cancer cells in the center of the CD44+ cell clusters persist." (PMID 19087284, 2008). "Dysregulated expression and splicing of cell adhesion marker CD44 is found in many types of cancer." (PMID 18793421, 2008). "The uPAR-positive cells expressed stem- and cancer cell markers, including CD44 and MDR1." (PMID 17327908, 2007). "Most widely studied CD44 in clinical cancers are probably CD44s, CD44v6, and CD44v3." (PMID 17343740, 2007). "CD44, keratins 7 and 8 are overexpressed in several different kinds of cancers." (PMID 12402156, 2002). "Beside cell-surface expression, the measurement of soluble CD44 in serum of cancer patients could be useful in early diagnosis and assessment of disease status." (PMID 8519665, 1995). "Furthermore, MIF inhibition in MASLD led to a reduction in integrinβ+CD44+ cancer cells." (PMID 41545340, 2026). "This counterintuitive role, where loss of expression is detrimental, highlights the context-dependent nature of CD44 in cancer biology and lends external support to our hypothesis that the CD44s-v5-v6 Null phenotype in CCA may represent a distinct and highly aggressive disease subtype." (PMID 41514534, 2025).
cancer (continued). "Indeed, it is well established that the upstream transcription factors could regulate CD44 expression in cancer cells." (PMID 40409554, 2025). "Besides physiological roles, CD44 was also described as a cancer stemness marker that may promote and support oncogenic processes like cell proliferation, migration, inflammation and angiogenesis, as well as endow cancer cells with drug resistance." (PMID 41327374, 2025). "Our data demonstrated that CD44 expression was elevated in cancer cells under steatotic liver conditions and was closely associated with the nearest CAF density that may amplify the HA-mediated signaling pathway to enhance the proliferation, invasion, and metastasis of CRC cells in the liver." (PMID 39946200, 2025). "The ongoing investigation into the role of CD44 variant exon v6 in cellular death pathways across various cancer types may not yet provide a comprehensive understanding for all cancers." (PMID 40114966, 2025). "Through the coordination with membrane-associated glycoproteins—including CD44, epidermal growth factor receptor (EGFR), integrins, CD280 (uPARAP/Endo180/MRC2), and CD276, CD147 orchestrates intracellular signaling events that drive cancer cell metabolic adaptation." (PMID 41479915, 2025). "Thus, targeting both cell death pathways and total CD44 signaling may offer a promising approach to overcoming chemoresistance in various cancers." (PMID 40114966, 2025). "Human cancer stem cells (CSCs) are a known targets of EGCG for cancer prevention and treatment; the fact that EGCG prevents the transcription and translation of genes encoding for stemness markers such as CD44, CD133, Nanog, Oct4, and Sox2 suggests that it averts CSCs from self‐renewing in general." (PMID 40255557, 2025). "Moreover, CD44 could maintain cancer stemness and CD44 knockdown can remarkably impair sphere formation and tumorigenicity in the xenograft model of colorectal CSCs." (PMID 41346572, 2025). "Disorders in CD44 function or expression lead to a wide range of abnormalities, including impaired leukocyte migration, chronic inflammation, excessive activation of fibroblasts and myofibroblasts, pathological tissue fibrosis, and increased invasiveness of cancer cells." (PMID 41009438, 2025). "Therefore, Zeb1, along with CD44, promotes cancer cell migration." (PMID 40806166, 2025). "Notably, CD44, a cancer stem cell marker, showed the highest expression in diffuse-type samples." (PMID 40849307, 2025). "Although we observed reduced CD44 expression in brain metastases compared to primary lung tumors, this finding appears to contrast with previous studies reporting a critical role of CD44+ cancer-stem-cell (CSC)-derived pericyte-like cells in promoting brain metastasis." (PMID 40805225, 2025). "In this regard, CD44s is overexpressed in mesenchymal stem-like cancer cells, but it is also expressed at various levels in non-cancer cell types, which could present a clinical challenge for anti-CD44 therapies due to a potential on-target toxicities in healthy tissues." (PMID 40342488, 2025). "However, the role of cell-surface CD44 in cancer has been studied more than its soluble form." (PMID 41440277, 2025). "In addition, we chose to investigate the interaction of R-RAS2 with CD44 because it is considered an important marker of cancer stemness, because it is involved in EMT and because it promotes metastasis through interaction with the ECM, most importantly with hyaluronic acid." (PMID 40221767, 2025). "Examination of key cancer-associated markers revealed distinct subtype-specific expression patterns, with the proliferation marker MKI67 showing higher expression in malignant subtypes 2 and 6, while the potential stem cell marker CD44 was elevated in subtype 3." (PMID 40650680, 2025).
cancer (continued). "In summary, the interaction of CD44 with HA and different CD44 isoforms regulates the ability of HA uptaking and expression have effect on cancer, which provides important advances with respect to cancer treatment strategies based on HA and the of selection of different CD44 isoforms as a target." (PMID 38783892, 2024). "Hence, well‐designed studies are needed to investigate the roles of CD44 isoforms in cancer." (PMID 37849446, 2024). "However, Treg infiltration was negatively correlated with CD44 in most cancers." (PMID 38590654, 2024). "Thus, antibodies targeting OPN receptors, CD44 or integrin could be administered for OPN-targeted cancer therapy." (PMID 39062100, 2024). "CD44 may be a molecular target for cancer therapy and an important prognostic marker." (PMID 38798768, 2024). "In studies involving human head and neck squamous cell cancer under deferoxamine-induced hypoxia, OXY pre-treatment inhibited cancer stem cell markers such as Oct-4, Nanog, CD-44, and CD-105, suggesting that OXY may prevent the epithelial–mesenchymal transition (EMT) and metastasis." (PMID 39334906, 2024). "A systematic review of landmark CD44‐related studies could facilitate a better understanding of the functional role of CD44 in cancer development and progression and thus will contribute to the development of novel strategies to circumvent their disadvantage and acquire optimal clinical efficacy." (PMID 38783892, 2024). "Interestingly, even in TβRIIiΔEC mice transplanted with LLC-GFP, decreased expression of CD44 was observed in pulmonary vascular ECs one month after tamoxifen administration, suggesting that TGF-β signaling regulates CD44 expression independently of the presence of cancer cells." (PMID 39758992, 2024). "Finally, IWP-2 treatment could also attenuate the expressions of markers of EMT (enhanced E-cadherin and reduced vimentin levels) and cancer stemness (reduced CD44 and Oct4a but increased CD24 levels) as seen in the castration-relapse VCaP-NURR1 tumors." (PMID 38531859, 2024). "Therefore, it is necessary to conduct a systematic analysis on the role of CD44 in pan-cancer." (PMID 38590654, 2024). "Furthermore, we could not ascertain the possible role of concurrent administration of HA in cancer chemotherapy, although it is known that hyaluronan affects the synthesis of molecules involved in its own pathway, including CD44." (PMID 38542115, 2024). "Therefore, we wondered whether miR-204 has a functional role in VM formation in MDA-MB-231 and Hs-578t cancer stem-like cells (CD44+/CD24−)." (PMID 38392969, 2024). "Additionally, the clinicopathological impact of CD44 suggests that it may be a molecular target for cancer therapy." (PMID 38672650, 2024). "The authors concluded that CD24 and CD44 could not be used as specific cancer stem cell markers for prognostic or diagnostic purposes." (PMID 39684268, 2024). "Moreover, cells were stained with CD24 and CD44 to assess the cancer stem-like phenotype." (PMID 38212739, 2024). "In addition, CD44 is a compelling marker for cancer stem cells of many solid malignancies." (PMID 39840036, 2024). "Therefore, targeting OPN/αvβ3 integrin and the OPN/CD44 signaling cascade may control epithelial-mesenchymal plasticity in various cancers." (PMID 39062100, 2024). "Among 439 cancer-free women in our study, we found inverse associations of age at first birth and the time between menarche and first birth with expression of CD44 and ALDH1A1 and positive, though marginally significant, associations of age at menarche with CD44 expression." (PMID 38577336, 2024).